HMGA1 (high mobility group AT-hook 1)
Diseases named in the same sentence as HMGA1 in open-access papers (continued):
Sharing a sentence is not in itself a finding about the gene and the disease.
lung cancer (continued). "In both analyzed subtypes of lung cancer, some dissimilarities in HMGA1 expression level were stated." (PMID 35805937, 2022). "The overexpression of the HMGA1 gene and its protein in lung cancer tissue, as well as their involvement in key signaling pathways in the development of the tumor, justified the search for their prognostic significance in lung cancer." (PMID 35948739, 2022). "Our findings indicate some connection between HMGA1 expression and the sex and smoking history of lung cancer patients." (PMID 35805937, 2022). "TCGA and TGEx data provided by the GEPIA platform was used to analyze the correlation between HMGA1 expression level and those of genes coding revealed protein interactors in lung adenocarcinoma, lung squamous cell carcinoma, and normal lung cancer tissue." (PMID 35805937, 2022). "It is most likely that the effect of the HMGA1 on the progression of lung cancer is dependent on some other factors." (PMID 35805937, 2022). "Taken together, the findings from the bioinformatical analysis indicate that elevated HMGA1 expression is a common feature of many malignant tumors, including lung cancer." (PMID 35805937, 2022). "Eleven of 34 analyses in 9 of 14 datasets collected in Oncomine found HMGA1 to belong to 10% of the top overexpressed genes in lung cancer." (PMID 35805937, 2022). "Saed and his colleagues have observed that HMGA1 presented higher expression in lung cancer specimens and overexpressed HMGA1 lead to dismal prognosis of LUAD." (PMID 36324565, 2022). "In contrast, a negative correlation was found between the mRNA expression level and the DNA methylation profile of HMGA1 in lung cancer." (PMID 35805937, 2022). "The data published so far cannot conclusively indicate that HMGA1 expression differs between different histological subtypes of lung cancer." (PMID 35805937, 2022). "In the present study, survival analysis indicates the high HMGA1 expression level is connected with poor survival of lung cancer patients." (PMID 35805937, 2022). "Our own analysis of the data provided by cBioPortal found that the genomic alterations of the HMGA1 gene occur very rarely in lung cancer tissue." (PMID 35805937, 2022). "A similar observation was made using the TIMER2.0 database where lung cancer was found to be among the neoplasms most significantly overexpressing the HMGA1 (p < 0.001)." (PMID 35805937, 2022). "The data about the role of the HMGA1 gene and its protein in lung cancer pathogenesis and prognostication is also limited." (PMID 35805937, 2022). "Overall and first progression survival of lung cancer patients was shorter when HMGA1 expression was high, according to the Kaplan–Meier plotter." (PMID 35805937, 2022). "The significant role played by HMGA1 expression in promoting growth, invasiveness, and migration of lung cancer cells in vitro has been confirmed." (PMID 35805937, 2022). "In studies of kidney, liver, breast, and lung cancers, inhibition of HMGA1 reportedly the performance of pAKT and inhibited tumor growth and metastasis." (PMID 35629376, 2022). "Some studies provide evidence that HMGA1 is responsible for carcinogenic dysregulation of crucial gene pathways or miRNAs in many tumor types, including lung cancer." (PMID 35948739, 2022). "When we overexpressed HMGA1 in HMGA1 siRNA-transfected lung cancer cells to restore HMGA1 expression, we rescued AGT promoter activity in these cells." (PMID 33380422, 2021). "We conclude that although KLF6 promotes AGT gene transcription when oncogenic K-Ras is expressed in normal cells, HMGA1 promotes AGT expression in lung cancer cells expressing oncogenic K-Ras." (PMID 33380422, 2021). "HMGA1 has been reported to play an important role in many types of cancers, including lung cancer, colorectal cancer, breast cancer, cervical cancer, and BC." (PMID 32477928, 2020). "MiR-222 was reported to be regulated by HMGA1 which can promote cell proliferation through binding to the promoter of miR-222 in lung cancer." (PMID 32477928, 2020).
lung cancer (continued). "We then explored the function of HMGA1 in lung cancer by knocking down its expression in PC9 and PC9/gef cells." (PMID 28290473, 2017). "Further, we observed a strong and inverse correlation between HMGA1 gene expression and overall survival in patients diagnosed with lung cancer." (PMID 27602961, 2016). "Further, studies have shown that HMGA1 overexpression is involved in the dysregulation of numerous oncogenic genes and miRNAs in many tumor types, including lung cancer." (PMID 27602961, 2016). "In contrast, strong nuclear and higher HMGA1 expression was observed in lung cancer tissues compared to the expression in normal lung tissues." (PMID 27602961, 2016). "Studies using miR-222-3p inhibitor and mimic showed that IL-24wt mediates AKT inhibition in lung cancer cells by regulating the HMGA1/miR-222 node." (PMID 27602961, 2016). "Kaplan-Meier survival curve analysis of 1926 lung cancer patients showed that patients with high HMGA1 gene expression had low overall survival compared to patients with low HMGA1 expression." (PMID 27602961, 2016). "Our recent observation of IL-24-mediated AKT inhibition in lung cancer cells and results from another study indicating that the HMGA1/miR-222 axis is involved in AKT regulation prompted this line of investigation." (PMID 27602961, 2016). "Further, the expression levels of IL-24, and HMGA1 proteins were analyzed in cultured human lung cancer cells (H1299, A549, HCC827, H460, and H358) and human normal lung fibroblasts (MRC-9, CCD16, and WI38)." (PMID 27602961, 2016). "Our results demonstrate for the first time that IL-24 inhibits AKT via regulating the HMGA1/miR-222 signaling node in human lung cancer cells and acts as an effective tumor suppressor." (PMID 27602961, 2016). "Another two pro-oncogenic miRNAs that can also target HMGA1, miR-196a-2 and miR-155, are upregulated in lung cancers." (PMID 24564251, 2013). "HMGA1 (High Mobility Group AT-Hook 1) has been related to lung cancer." (PMID 37920509, 2023). "However, only a few research reports about the importance of the HMGA1 gene and HMGA1 protein expression as a prognostic factor in lung cancer are published to date." (PMID 35948739, 2022). "Taken together, it appears that HMGA1 can play an important role in pulmonary carcinogenesis and also could be a promising prognostic biomarker or therapeutic target in lung cancer." (PMID 35805937, 2022). "The study also examined whether an increase in HMGA1 mRNA expression in lung cancer is followed by an elevation of HMGA1 protein." (PMID 35805937, 2022). "Especially, the possibility to identify very little amounts of HMGA1 transcripts directly in the blood specimens could either allow for early diagnosis or the monitoring of the efficacy of lung cancer therapy." (PMID 35805937, 2022). "In light of the results of our analysis, the evaluation of HMGA1 expression level may be of great value in the management of lung cancer patients." (PMID 35805937, 2022). "HMGA1 overexpression in lung cancer could result from reduced HMGA1 methylation and this is connected with some clinicopathological features and adverse prognosis of lung cancer patients." (PMID 35805937, 2022). "As HMGA1 is an upstream negative regulator of the EGFR signaling pathway, it could be speculated that gender-specific HMGA1 expression influences lung cancer cell behavior." (PMID 35805937, 2022). "Considering the limited knowledge about the role of the HMGA1 in lung cancer transformation as well as putative prognostic, predictive, and therapeutic value of the gene, we aimed to appraise the importance of the HMGA1 expression level in tissue and blood samples of NSCLC patients." (PMID 35948739, 2022). "Taken together, HMGA1 overexpression could be an essential element of lung carcinogenesis and a prognostic feature in lung cancer." (PMID 35805937, 2022). "HMGA1 overexpression observed at the mRNA level is a common feature of lung cancer." (PMID 35805937, 2022).
lung cancer (continued). "Additionally, the gene chip data provided by TNMplot indicated significant differences in HMGA1 expression level between normal lung tissue and lung cancer tissue-primary and metastatic samples (p = 0.0000)." (PMID 35805937, 2022). "The TNMplot platform tool was used to compare the HMGA1 expression level between paired lung cancer tumors and adjacent normal tissue collected from the same patients and between non-paired tumors and normal lung tissues collected from separate subject cohorts." (PMID 35805937, 2022). "Interestingly, we find that expression of AGT remains elevated in lung cancer cells but in a Kruppel-like factor 6–independent and high-mobility group AT-hook 1–dependent manner." (PMID 33380422, 2021). "Interestingly, an association between the expression of SIRT1, known to be induced by R, and HMGA1 was highlighted in lung cancer." (PMID 34439473, 2021). "Downregulation of HMGA1 by siRNA inhibited AGT promoter activity in A549 lung cancer cells." (PMID 33380422, 2021). "miR‐4458 can restrain migration and EMT through targeting HMGA1 in lung cancer." (PMID 33169939, 2020). "Further characterization of this regulatory mechanism may advance our understanding of the maintenance of lung cancer phenotypes and uncover a novel therapeutic intervention point for tumors driven by HMGA1." (PMID 33505435, 2020). "While HMGA1 is known to be deregulated in lung cancer, the mechanisms that mediate its expression remain unknown." (PMID 30405205, 2018). "The current understanding of the role of HMGA1 in lung cancer is limited." (PMID 28290473, 2017). "To understand how silencing of HMGA1 is involved in recovering the sensitivity of genifitinib in lung cancer cells, we utilized phospho-kinase array to investigate which signaling pathways were activated after knocking down the expression of HMGA1 in PC9/gef cells." (PMID 28290473, 2017). "Finally, our study results provide a basis for the development of an IL-24/HMGA1-based therapeutic approach for lung cancer treatment." (PMID 27602961, 2016). "In the present study, we determined whether (i) IL-24 mediates inhibition of HMGA1 expression in lung cancer cells and (ii) IL-24 mediates AKT inhibition through HMGA1 suppression." (PMID 27602961, 2016). "Thus, a therapy combining IL-24 with HMGA1 siRNA or miR-222-3p inhibitor should present effective treatment of lung cancer." (PMID 27602961, 2016). "However, the exact role of HMGA1 in lung cancer pathogenesis is not fully understood." (PMID 35948739, 2022). "However, the low occurrence of HMGA1 amplification or point mutation in lung cancer excludes the possibility that genomic alterations of HMAG1 are responsible for the common overexpression of HMGA1 in this type of tumor." (PMID 35805937, 2022). "Additionally, HMGA1 could also contribute to the poor outcome of lung cancer treatment using both conventional and targeted drugs." (PMID 35948739, 2022). "High expression levels of HMGA1 mRNA in lung tumors and relatively low expression levels in non-cancerous tissue of the lung allow us to assume that such therapies would have clinical advantages in lung cancer because of presumed low toxicity toward healthy cells." (PMID 35805937, 2022). "In conclusion, our results showed that IL-24wt inactivates AKT by suppressing the HMGA1/miR-222 axis and that the combination of IL-24wt with HMGA1 silencing and miR-222 inhibitors was more effective in attenuating AKT and the associated lung cancer migration and invasion." (PMID 27602961, 2016). "FOXM1 is overregulated in nine lung cancer datasets and is related to: 1) the negative regulation of transcription along with E2F1, FOXE1, and HMGA1; 2) cellular senescence along with E2F1, E2F3, and MYBL2; and 3) DNA repair and damage." (PMID 39228892, 2024). "siRNA-mediated knockdown HMGA1 in combination with IL-24 reduced markedly AKT expression and substantially reduced migration and invasion of cultured lung cancer cells." (PMID 35948739, 2022).
lung cancer (continued). "Among the 363 up-regulated genes, 32 are prognostic markers in lung cancer, all of unfavorable prognosis, including LRP8, NUP62CL, FSCN1, PLCD3 or HMGA1." (PMID 36544755, 2022). "Thus, it could be concluded that the HMGA1 expression level could be a lung cancer biomarker." (PMID 35805937, 2022). "Further, studies have shown that both HMGA1 and AKT play an important role in lung cancer metastasis." (PMID 27602961, 2016). "Moreover, HSPA9 blocks the degradation of high mobility group A1 (HMGA1) and promotes the activation of the HMGA1/JNK/c-Jun axis in lung cancer to stimulate cancer cell growth and metastasis." (PMID 39261452, 2024). "Our findings indicate that the MVK, GGPS1 and PMVK expression was correlated with HMGA1 gene expression in lung cancer tissues, but not in normal lung tissue." (PMID 35805937, 2022). "Population affinity did not give rise to any significant differences in the HMGA1 expression in any of the analyzed subtypes of lung cancer." (PMID 35805937, 2022). "The data from Oncomine confirmed no substantial change in copy number variation of HMGA1 across different lung cancer subtypes." (PMID 35805937, 2022). "Since DNA methylation can change the gene activity without changing the sequence, the connection between the HMGA1 expression level and DNA methylation profile in lung cancer was inspected using cBioPortal." (PMID 35805937, 2022). "Finally, downregulation by siRNA of HMGA1, a positive regulator of AGT transcription in lung cancer cells, inhibited growth in soft agar of H460 cells." (PMID 33380422, 2021). "Our results provide a comprehensive insight into the regulatory role of MCM2 in lung cancer, and also reveal that MCM2 promotes cell proliferation might possibly via the regulation of high mobility group protein HMG-I/HMG-Y (HMGA1) phosphorylation." (PMID 29038488, 2017). "Therefore, HMGA1, a regulator of the PI3K/AKT/mTOR pathway, is a potential target for lung cancer treatment." (PMID 27602961, 2016). "To determine whether the observed combined inhibitory effect of IL-24 and HMGA1 siRNA on HMGA1 signaling was restricted to one cell line, we performed experiments in an additional HCC827 lung cancer cell line." (PMID 27602961, 2016). "Similarly, in the present study, HMGA1 expression level was found to increase from non-tumor lung tissue through lung primary tumor to lung cancer metastasis." (PMID 35805937, 2022). "To assess IL-24 and HMGA1 protein expression in normal lung and lung tumor tissues, we performed immunohistochemistry (IHC) in a commercially available tissue microarray (TMA; BC041115b; US Biomax, Inc.), consisting of paired samples of lung cancer tissues and corresponding normal tissues." (PMID 27602961, 2016). "Finally, RNA profiling of lung epithelial cells (BEAS-2B) expressing a mutant allele of PIK3 (E545K) identified a network of transcription factors such as MYC, FOS and HMGA1, not previously recognised to be associated with aberrant PI3K signalling in lung cancer." (PMID 22363436, 2012). "Upregulation of HMGA1 gene expression has been reported in both adenocarcinoma and squamous cell carcinoma of NSCLC, and HMGA1 protein was detected in a high proportion of lung cancer tumors irrespective of the histological type." (PMID 35805937, 2022).
pancreatic cancer (29 papers, 2003 to 2025). "High expression of HMGA1 was associated with poor survival in TCGA pancreatic cancer patient cohort." (PMID 37190324, 2023). "HMGA1 gene expression has been associated with a high degree of malignancy, metastatic tendency, and poor survival in breast, colon, ovary, and pancreatic cancers." (PMID 35805937, 2022). "Furthermore, a higher expression level of HMGA1 was associated with worse overall survival and disease-free survival in patients of TCGA pancreatic cancer cohort." (PMID 37190324, 2023). "For example, in models of pancreatic cancer, we discovered that HMGA1 activates pathways downstream of the fibroblast growth factor, FGF19, and inhibitors of FGF19 and its receptor (FGFR4) are already available in the clinic." (PMID 40076747, 2025). "Hmga1 is overexpressed in several types of cancer, including breast, colorectal, and pancreatic cancers." (PMID 40182023, 2025). "Given the association between anoikis resistance and the PI3‐K/Akt pathway, HMGA1 was regarded as a potential therapeutic target for pancreatic cancer." (PMID 39286778, 2024). "Here, high expression of HMGA1 and HMGA2, two important members of the HMGI/HMGY family, was significantly associated with a poor prognosis in patients with pancreatic cancer." (PMID 37370109, 2023). "HMGA1 in pancreatic cancer is resistant to gemcitabine by an Akt-dependent mechanism, but stable short hairpin RNA targeting HMGA1 can resensitize drug-resistant cells." (PMID 35864955, 2022). "Under normal conditions, pancreatic cancer cell-derived exosomes promote angiogenesis by regulating the CCAT1/miR-138-5p/HMGA1 axis." (PMID 36230535, 2022). "HMGA1 overexpression has been noted in in breast, colon, ovarian, and pancreatic cancer, among others." (PMID 35805937, 2022). "Metformin upregulates miR-26a, which inhibits HMGA1 expression to affect pancreatic cancer progression." (PMID 35864955, 2022). "CCAT1 competitively bound to miR-138-5p to regulate downstream HMGA1 expression, and ultimately affected the progression of pancreatic cancer." (PMID 34660700, 2021). "Most notably, the AT-rich phosphorothioate aptamer (AT-sDNA) increased the sensitivity of Miapaca-2 and AsPC-1 pancreatic cancer cell lines to gemcitabine treatment, presumably by acting as a decoy to bind to excess HMGA1." (PMID 28703779, 2017). "Pancreatic cancer is poorly treated by conventional chemotherapies including gemcitabine due to the profound chemoresistance through widely expressed HMGA1." (PMID 22348037, 2012). "More recently, we found that HMGA1 protein levels correlate with poor differentiation status and decreased survival in pancreatic cancer, further implicating HMGA1 in an undifferentiated, stem-like state and tumor progression." (PMID 22276142, 2012). "Elevated HMGA1 levels play a critical role in pancreatic cancer tumorigenesis." (PMID 41183073, 2025). "For instance, HMGA1 was found to promote anoikis resistance in pancreatic cancer cells through PI3‐K/Akt‐dependent mechanism, whereas inhibition of PI3‐K/Akt by the small molecule inhibitor LY294002 or dominant‐negative Akt could reverse this cell fate." (PMID 39286778, 2024). "Furthermore, c-Myc overexpression in pancreatic cancer cells with GATM knockdown restored HMGA1 and HMGA2 expression." (PMID 37370109, 2023). "Consistent results were observed from the HMGA1 staining on human pancreatic tumors." (PMID 37190324, 2023). "In addition, in patients with pancreatic cancer, HMGA1 promotes tumor development through the PI3-K/Akt cellular signaling pathway, and thus elevated HMGA1 expression is associated with poor prognosis." (PMID 35629376, 2022). "The hypothesis that suppression of HMGA1 is a determinant for the antiproliferative and antimigratory activities of Met comes from studies using cell lines of pancreatic carcinoma and nude mice xenografts." (PMID 36506071, 2022).